CD4 (CD4 molecule)
Diseases named in the same sentence as CD4 in open-access papers (continued):
Sharing a sentence is not in itself a finding about the gene and the disease.
cancer (continued). "Both, CD4+ and CD8+ T cells were detected within cancer cell nests and sporadically in the mesenchymal stroma." (PMID 35630004, 2022). "The ACK1 kinase not only suppressed T-cell activation but also a key chemokine, CXCL10, which plays a crucial role in directing the migratory properties and potentiation of CD4+ and CD8+ T cells in the context of cancer and inflammatory autoimmunity." (PMID 36376335, 2022). "The model includes CD4+ and CD8+ T cells, dendritic cells, and cytokines by which these cells interact, as well as cancer cells (androgen-independent (M) and androgen-dependent (N)), and drugs." (PMID 35015785, 2022). "Taken together, it appears that NTP treatment can transiently potentiate the next steps of the cancer‐immunity cycle in the TDLN as more CD8+ and non‐regulatory CD4+ T‐cell activation was measured along with less exhaustion." (PMID 36176603, 2022). "Comparing the absolute pathway activity scores of TIL samples with the pathway scores measured in the in vitro cancer SN study, TIL-derived CD4+ T cells mostly resembled in vitro activated CD4+ T cells that were incubated with the cancer tissue SN." (PMID 35158758, 2022). "Most clinical applications of T cells are centered on αβ T cells (CD4+, CD8+ T cells); however, γδ T cells also have important roles in cancer immunity." (PMID 35407555, 2022). "Various immune cells in TME were involved in cancer prognosis, including adaptive immune CD8+/CD4+ T-lymphocytes, NK cells, MDSCs, dendritic cells, macrophages, and so on." (PMID 35326741, 2022). "Natural killer (NK) cells, CD4+ T cells, and CD8+ T cells play essential roles in cancer development." (PMID 36091768, 2022). "The expression of ASCL2 was significantly correlated with the infiltration levels of CD4+ T cells, CD8+ T cells, B cells, neutrophils, and dendritic cells in various cancer types, including COAD." (PMID 35774798, 2022). "The single-cell RNA-seq analysis revealed that the number of CD4+ T cells, CD8+ T cells, B cells, and cancer stem cells (CSCs) were altered significantly in the MSI group compared with the MSS group." (PMID 35774798, 2022). "Specifically, activated CD8+, CD4+ T cell, NK cell, etc., were observed more in the TME of MSI-H cancers, except for CD56 bright NK cell, which produces great levels of cytokine." (PMID 35433823, 2022). "CD4+ and CD8+ T cells with activity against IDO1+ and PD-L1+ cancer and immune cells were detected in the blood of the vaccinated patients." (PMID 36275666, 2022). "In contrast, the infiltration level of CD4+ central memory T cells and CD4+ effector memory T cells was found negatively correlated high LMNB1 expression in more than half of the TCGA cancer kinds." (PMID 35241075, 2022). "The results revealed that ASCL2 was highly correlated to the infiltration levels of CD4+ T cells, CD8+ T cells, B cells, neutrophils, and dendritic cells in the vast majority of cancer types." (PMID 35774798, 2022). "We therefore sought to determine if there was a different immune response in the TME between men and women by direct counting of CD4+ and CD8+ T cells, and by profiling immune and cancer related gene expression between sexes." (PMID 36387163, 2022). "Negative associations were found between the frequencies of CD4+CD25+Foxp3+ and CD4+CD25+Foxp3+CD127low/− Treg cells and cancer stage (P = 0.015 and P = 0.059)." (PMID 36376825, 2022). "The results showed that in the TME of many cancers, FDX1 had a good correlation with various types of immune cell invasion (CD4+ T cells, Macrophages, B cells, T cells regulatory, Mast cells resting, etc.)." (PMID 35991547, 2022). "CD4+ Th1 cells secrete IL-2 and IFN to activate and promote the proliferation of CD8+ T cells, which subsequently release cytotoxic cytokines and kill cancer cells directly." (PMID 35061208, 2022).
cancer (continued). "Since DSP107 potently triggered 4-1BB costimulatory signaling, its effect on T cell-mediated killing of cancer cells was assessed by co-culture of isolated CD3+, CD4+, or CD8+ T cells with the CD47-positive NHL line SC-1.scFvCD3." (PMID 35287686, 2022). "UNC5A level was significantly related to the infiltration of B cells in 10 diverse cancer types, CD4+ T cells in 21 various cancer types, CD8+ T cells in 9 cancers, neutrophils in 18 cancers, macrophages in 16 cancers, and dendritic cells in 18 cancers." (PMID 36551254, 2022). "The effect of CCL5 was diminished after inhibiting CD4+ T cells, suggesting that Th cells mediate CCL5-induced cancer-promoting phenotypes of TAMs." (PMID 35740686, 2022). "There is considerable interest in utilizing DCs to stimulate antigen-specific anti-tumoral CD4+ and CD8+ T cell responses in cancer immunotherapy." (PMID 35979362, 2022). "The clustering heat map of the relationship between TOP1MT and immune cells demonstrated a positive correlation of TOP1MT with B cells and CD4+T lymphocytes in KIPP and LIHC cancers and with purity in BLCA and HNCC." (PMID 36035140, 2022). "In the elimination phase of HCC, emerging cancer cells can be recognized and killed by many immune cells, such as CD8+ and CD4+ T cells." (PMID 35027925, 2022). "Nearly all highest ranked simulations use the highest CAR T-cell dose, a CD4+:CD8+ ratio of 25:75, the lowest CAR affinity, and the highest cancer antigen level." (PMID 35903149, 2022). "Accordingly, the numbers of active CD4+ and CD8+ T cells were apparently reduced by increasing RelB in the cancer cells." (PMID 35177112, 2022). "The accumulation of CD4+ and CD8+ T cells, which fuels cancer growth and metastases, can be used to predict the prognosis of cancer patients." (PMID 35799889, 2022). "Blockade of CD5 also demonstrated increases in both CD4+ and CD8+ T cell responses to cancer, indicating that its inhibitory effects can be halted by antibody blockade." (PMID 35327505, 2022). "CD4+ T cells provide cytokine support for CD8+ T cell proliferation and expansion to destroy cancer cells and trigger antitumoral responses." (PMID 36142615, 2022). "Our study disclosed that m7G scores were negatively correlated with CD4 T cells, CD8 T cells and NK cells but positively correlated with Treg cells in most of cancer types, while the concrete mechanisms are still in a mist." (PMID 36092891, 2022). "We next estimated the associations between the expression of cooperative lncRNAs and infiltration levels of six immune cells (B cells, CD4 T cells, CD8 T cells, macrophages, neutrophils, and dendritic cells) in each cancer." (PMID 36463330, 2022). "CD27, expressed by CD4, CD8 T lymphocytes, and NK cells, plays an important role in cancer immunotherapy." (PMID 35392242, 2022). "CD4+, CD8+, and NK cells, as cytotoxic lymphocytes (CTL), can eliminate cancer cells resulting in the inhibition of cancer development." (PMID 36131791, 2022). "The cancer incidence rate increased with more advanced WHO clinical stage and decreasing CD4 counts at ART initiation." (PMID 34873875, 2022). "Overall, the pan-cancer expression level of CD45 was positively correlated with the presence of multiple immune infiltrates, such as CD4 (+) memory T cells, CD8 (+) T cells, myeloid dendritic cells and macrophages." (PMID 36061172, 2022). "Multiplex immunofluorescence evaluated T-cell density and %PD-1 expression after HIPEC within cancer islands and stroma of CD8+ T cells and CD4+ conventional T cells." (PMID 35357903, 2022). "In this section, we will discuss current evidence for CD4 CTL targeting and triggering in cancer immunotherapy." (PMID 35572552, 2022). "Effective treatments have the highest doses of CAR T-cells, weaker CARs, CD4+:CD8+ ratios of 25:75 or 50:50, and higher cancer cell antigen count." (PMID 35903149, 2022).
cancer (continued). "Immune suppression by cancer is related to a decrease in TCR diversity and a decrease in activated CD4+ CD8+ lymphocytes, whereas a patient’s immune capacity refers to a physical ability to sufficiently replenish these lymphocytes when they are exhausted." (PMID 36291893, 2022). "TIM-3 showed the highest levels on both CD8+ and CD4+ T cells, and importantly, TIM-3 levels were similar to those in immunotherapy-responsive cancers." (PMID 36359346, 2022). "Such as malignant tumors, hereditary immunodeficiency diseases, AIDS, and CD4+T lymphocyte depletion in patients on immunosuppressive drugs." (PMID 36741380, 2022). "There was a significant increase in vaccine-specific responses in blood detected in vitro with vaccine-reactive T cells comprising CD4 + and CD8 + T cells with activity against IDO- and PD-L1-expressing cancer and immune cells." (PMID 35672823, 2022). "Half of the PLWH who developed an incident cancer (n = 33, 50.0%) had initiated ART with CD4 counts below 100 cells/mm3." (PMID 34873875, 2022). "For peptide-based cancer vaccines to work, they need CD8+ epitopes to use the antigen cross-presentation pathway, which activates CTL anti-tumor immunity, and CD4+ epitopes to activate T-helper cells, which keeps the CTL effector function going." (PMID 36552988, 2022). "Our results indicate that most cancers are not only related to T cell CD8+, T cell CD4+, neutrophils, myeloid dendritic cells, macrophages, and B cells." (PMID 35860430, 2022). "TIM-3 expression by regulatory lymphocytes (CD4+) is correlated with disease progression in NSCLC, ovarian cancer (OC), prostate cancer (PC), and other types of cancer." (PMID 36140182, 2022). "Venetoclax enhances CD8 T-cell killing of autologous HIV-infected CD4 T cells, including following reactivation from latency, and venetoclax also augments CD8 T-cell mediated clearance of cancer cells." (PMID 36448802, 2022). "Numerous studies have indicated that the immune system of cancer patients is weak, including increased CD3+CD8+ T cells and decreased CD3+CD4+ T cells, CD4+/CD8+ ratio, and NK cells." (PMID 35865086, 2022). "The cells, especially the CD4+ T cells, CD8+ T cells, B cells, cancer stem cells, and enterocytes, were significantly altered in the MSI group compared to the MSS group." (PMID 35774798, 2022). "The ratio of CD4+/CD8+ cells acts as an indicator of immune function and reflects the immunological status in cancer patients." (PMID 36555814, 2022). "This supports that treatment with Salmonella + Alb-IL2 drives the proliferation of CD4 and CD8 T cell populations which likely contributes to the observed anti-cancer effects." (PMID 35962391, 2022). "CD4 and CD8 T cells are two well-known lymphocytes, which play a vital role in cancer immune response." (PMID 35739249, 2022). "The data reported here revealed a strong correlation between CD4, CD25 and FoxP3 markers, indicating a high incidence of Treg cells, which in turn correlated with dysplastic progression to carcinoma." (PMID 36009387, 2022). "We next performed an analysis of peritoneal CD4+ and CD8+ T cells in cancer patients with peritoneal metastases to assess the feasibility of peritoneal lavage harvest for ACT in these patients as a correlate to our findings in murine models." (PMID 33679747, 2021). "CD70/CD27 costimulatory signaling has been reported to be the key mechanism to deliver CD4+ T cell help from DC to CD8+ T cells, and contribute to their clonal expansion and differentiation into effector and memory CTL in cancer and viral infections." (PMID 34012451, 2021). "First, we found that the percentage of cancer cells correlates with the percentage of CD8+ T cells, CD4+ T cells, and Tregs." (PMID 32808188, 2021). "In particular, studies have found a critical role for interleukin (IL)-21, a cytokine produced primarily by CD4+ T cells, in facilitating a CD8+ T cell response in both cancer and chronic infection." (PMID 33809259, 2021).
cancer (continued). "Key HIV-related prognostic indicators such as nadir CD4 count and median VL were important with onset of anal HSIL and cancer diagnoses." (PMID 33596943, 2021). "Cell-mediated immunity is an important adaptive immune response to combat tumors in the cancer microenvironment, which includes the actions of Th cells (CD4+), CTL (CD8+), and Treg cells (CD4+/CD25+)." (PMID 34371830, 2021). "Finally, as the role of CD4+ T cell lymphocytes in immune surveillance and activity against cancerous cells becomes more apparent, with recent evidence suggesting a role in advancing and maintaining anti-cancer activity, TGF-β appears to suppress CD4+ TH cell proliferation." (PMID 34830879, 2021). "PD-1 is a crucial immune checkpoint molecule that inhibits the function of CD4+ and CD8+ T-cells in the TME and regulates its function during different physiological responses such as cancer, autoimmunity, and infection." (PMID 33546207, 2021). "The median ALC and lymphocyte subsets (CD3, CD4, CD8, Treg, NK and B cells) were significantly lower in cancer patients, while median fibrinogen levels (p < 0.001) and IL‐6 (p < 0.001) were significantly higher in cancer cohort." (PMID 34786866, 2021). "We overlay BABEL’s predicted expression on the ATAC-based UMAP projection for these cells, which consist of several populations of CD4+ and CD8+ T cells, B cells, NK cells, malignant tumor cells, among others." (PMID 33827925, 2021). "Tregs are central agents responsible for modulating immunity by inhibiting CD4+T helper, CD8+T, and B cells in cancer." (PMID 34660294, 2021). "Patients were categorized into low and high HNF1B expression groups based on the CD4+ T cell, CD8+ T cell along with B‐cell levels, which were further grouped based on overall survival of cancer patients into different subsets." (PMID 33580750, 2021). "Less research has been reported on the role of peripheral blood immune cells in advance cancer stage, which focus on B cells, NK cells, CD4+ T cells, CD8+ T cells and CD4+/CD8+." (PMID 34488711, 2021). "We identified significant differences in the CD4+ T cell count between HIV-infected individuals developing HL and HIV-infected matched controls within 1 year before cancer diagnosis." (PMID 33865435, 2021). "On the other hand, other subsets, i.e., CD3+ pan T cells, CD4+ helper T cells, CD8+ cytotoxic T cells, and CD45RO+ memory T cells, are also considered important players in adaptive and cancer immunity." (PMID 34572935, 2021). "They present the antigens through MHC class I and II to the CD4+ and CD8+ lymphocytes triggering the immune response process towards cancer cells." (PMID 33902630, 2021). "NK cells, and CD4+ and CD8+ T cells play a crucial role in cancer immunosurveillance, and moxibustion has been shown to have an important regulatory effect on these cells." (PMID 33506637, 2021). "In general, cancers with a pCR were positive for the 27-gene IO signature and tended to have higher proportions of CD8+ T cells, CD4+ T cells, proinflammatory M1 macrophages, and dendritic cells, consistent with an immune-activated TME." (PMID 34638323, 2021). "There was a positive correlation between PD-L1+ cancer cells and both CD3 (r = 0.264, p = 0.02) and CD4 (r = 0.408, p = 0.0002) antigens." (PMID 33625532, 2021). "Therapeutic cancer vaccines aim to stimulate antitumor immunity, e.g., by supporting the activation of cancer-specific CD8+ and CD4+ T cells." (PMID 34830945, 2021). "We investigated neutrophils (CD45+ CD66b+), CD8+ T cells (CD3+CD8+), and CD4+ T cells (CD3+CD4+) in addition to PD-1 and PD-L1 expression in 25 tissue samples that were available from the cancer cohort." (PMID 35048057, 2021). "The immune response against cancer is generated by effector T cells, among them cytotoxic CD8+ T cells that destroy cancer cells and helper CD4+ T cells that mediate and support the immune response." (PMID 33924428, 2021).
cancer (continued). "PLWH treated with PIs were less likely to have CD4 count greater than 200 at time of HIV diagnosis (38.6%, n = 59 vs 63.6%, n = 42; p < 0.01) or at time of cancer diagnosis (66.0%, n = 101 vs 87.9%, n = 58; p < 0.01)." (PMID 34225709, 2021). "We noticed that SLC12A5 expression was distinctly correlated with the level of immune infiltration of B cells in 15 types of cancers, CD8+ T cells in 10 types of cancers, CD4+ T cells in 22 types of cancers, and macrophages in 16 types of cancers." (PMID 34630736, 2021). "The lymphocytes, CD4+ T cells, CD8+ T cell counts, and the ratio of CD4+ T cells to CD8+ T cells in cancer patients decreased more significantly." (PMID 34277701, 2021). "Cells with antitumor effects, such as CD8+ T cells, CD4+ T cells, B cells and plasma cells, presented negative correlations with the Riskscore, while cells with pro-cancer functions, such as M2 macrophages and cancer-associated fibroblasts, presented positive correlations." (PMID 34587919, 2021). "As anti-CD4 monoclonal antibody depletes CD4+ immune-suppressive cells, the combination of anti-CD4 treatment and ACT has synergistic potential in cancer therapy." (PMID 34493727, 2021). "In 7 of these cancers, the expression of FANCE was significantly negatively correlated with the infiltration level of CD4 + T cells." (PMID 33592580, 2021). "There were fewer CD3+, CD4+, and CD8+ cells in cervical lesions and more cells in cancers compared to normal epithelium." (PMID 33257839, 2021). "In summary, Rap1b expression was correlated with prognosis in 10 types of cancer, especially in KICH, LIHC, PAAD, MESO, and with increased immune infiltration levels of B cells, CD4 + T cells, CD8 + T cells, neutrophils, dendritic cells in various cancers." (PMID 34346294, 2021). "Patients with LSCC had a significantly lower percentage of circulating iNKT cells, compared to healthy controls, whereas circulating CD4+CD161+ T cells, representing a memory T cell population, significantly increased in cancer patients." (PMID 33917480, 2021). "In this paper, we present an attractive model of exhaustion of CD4+ T cells by PD-L1 expressing MDA-MB-231 and 786-O cancer cell lines." (PMID 34439305, 2021). "An imbalance between TH1 and TH2 subsets of CD4+ T cells with a tendency for immunological polarization toward the TH2 phenotype has been confirmed in peripheral venous blood in patients diagnosed with CRC and may be associated with the progression of this cancer." (PMID 33625532, 2021). "ASM was also shown to play a major role in the regulation of immune CD4 and CD8+ T cells, macrophages and natural killer cells to abrogate cancer cell viability." (PMID 34768550, 2021). "ASB16-AS1 was positively correlated with B cells, T cells CD4+ and T cells CD8+ in most cancer types, and negatively correlated with macrophages, dendritic cells and neutrophils in some cancer types." (PMID 34709970, 2021). "CD4+ T cells that are reactive against a selected peptide from MDM2 have been developed and showed promising effects against cancer progression." (PMID 35071005, 2021). "Among HNSCC and non-cancer tissues, human papillomavirus (HPV)-positive HNSCCs exhibited the highest scores in various immune cell types, including CD4+ T cells, CD8+ T cells, B cells, plasma cells, basophils, and their subpopulations." (PMID 34373557, 2021). "For example, the use of electroporation to directly deliver CRISPR material to CD4+ T cells, CD34+ stem cells, cancer cells and embryonic stem cells has been shown." (PMID 34188916, 2021). "This inhibition is incomplete emphasizing that additional mechanisms, such as MMP14 on cancer cells and αV integrin on infiltrating immune cells, including CD8+ and CD4+ TIL, and DC28,36, can activate latent TGF-β within the TME." (PMID 34471106, 2021).